SIRPA (signal regulatory protein alpha)
Diseases named in the same sentence as SIRPA in open-access papers (continued):
Sharing a sentence is not in itself a finding about the gene and the disease.
tumor (continued). "One essential and well-studied function of CD47 related to tumor development is preventing phagocytosis via ligating with signal regulatory protein-alpha (SIRPα) on the surrounding phagocytes and evading destruction by using the innate and adaptive immune system." (PMID 37063284, 2023). "The binding of CD47 to SIRPα expressed on macrophages prevents the phagocytosis of tumor cells." (PMID 37108657, 2023). "Furthermore, we were able to further increase the anti-tumor response by blocking both the CD47/SIRPα axis and the sialic acid/Siglec axis." (PMID 37444515, 2023). "CD47 is a transmembrane protein that acts as a ligand for signal regulatory protein-α (SIRPα), which is expressed on macrophages, and this interaction inhibits the phagocytic property of macrophages, which leads to increased tumor growth via less antigen presentation." (PMID 36769180, 2023). "Blockade of CD47/SIRPα, the “don’t eat me” axis, promotes phagocytosis of tumor cells." (PMID 37510993, 2023). "To study the overcoming of resistance to therapeutic IgA therapy in cancer cells through CD47 blockade, we investigated the combination of IgA antibodies and disruption of the CD47/SIRPα axis, a well-studied myeloid checkpoint pathway, in the context of tumor cell killing by neutrophils." (PMID 37444515, 2023). "HRT alone decreased the tumor-associated macrophages (TAMs, CD45+CD11b+F4/80+) phenotype among CD45+ cells, which was further decreased by adding anti-SIRPα (P = 0.0004 for HRT vs. Iso control, P = 0.0308 for anti-SIRPα + HRT vs. HRT)." (PMID 37291116, 2023). "Furthermore, engineered hybrid cell membrane nanovesicles containing M2-to-M1 repolarization signals and expressing SIRPα prevented both local cancer recurrence and distant metastasis, through triggering an anti-tumor immune response." (PMID 37476156, 2023). "When CD47 binds to SIRPα on macrophages, it can promote the clearance of tumor cells." (PMID 37208386, 2023). "CD47 can bind to SIRPα on the surface of macrophages to convey the “don’t eat me” signal to macrophages, forming the antiphagocytic signaling axis, inhibiting phagocytosis of macrophages on tumor cells." (PMID 36911723, 2023). "The expression of CD47 on tumor cells is currently considered to be an immune-tolerance mechanism, as it can inhibit professional phagocytes from contractile engulfment of tumor cells by interacting with SIRPα." (PMID 37291116, 2023). "Therefore, strategies targeting the CD47/SIRPα axis to enable tumor cell killing through cellular phagocytosis have emerged as promising cancer immunotherapies." (PMID 37706196, 2023). "To investigate the role of SIRPα expression in the modulation of macrophage phenotypes in vitro, we cultured WT and KO BMDMs respectively with LLC‐derived conditional media (LLC‐CM) for 24 h to obtain tumour‐associated macrophages (TAMs)." (PMID 36419386, 2023). "Briefly, the CD47 cell surface receptor on tumor cells forms a complex with signal-regulatory protein alpha (SIRPα) on phagocytic cells, resulting in the recruitment of SHP-1 and SHP-2 that prevent the accumulation of myosin IIA in the phagocytic synapse, ultimately inhibiting phagocytosis." (PMID 37373873, 2023). "The study suggests that a combination of blocking different inhibitory interactions, such as CD47/SIRPα and sialic acids/Siglec, may be necessary to optimize cancer immunotherapy, considering the ways in which tumor cells evade the immune system." (PMID 37444515, 2023). "Moreover, the anti-tumor functions of macrophages can be enhanced through nanobody-mediated blockade of the CD47/SIRPa pathway, reprogramming of macrophages from M2 to M1 phenotype and depletion of TAMs from the TME." (PMID 36761751, 2023). "Consequently, preventing CD47/SIRPα cross-talk stimulates the innate and adaptive immune responses, resulting in tumor-cell apoptosis." (PMID 38033495, 2023).
tumor (continued). "SIRPα is a transmembrane glycoprotein specifically expressed on myeloid cells and provides a “do not eat me” signal after engaged with integrin‐associated protein CD47 on tumour cells." (PMID 36419386, 2023). "Blockade of the interaction between CD47 and SIRPα could restore phagocytic activity and eliminate tumor cells in vitro and in vivo." (PMID 35418166, 2022). "Disrupting the interaction between CD47 and SIRPα may therefore promote anti-tumor effects by neutrophils and macrophages." (PMID 35884427, 2022). "In addition to promoting macrophage immunotherapy when used in combination with CD47/SIRPA blockers, BP nanoparticles can also be used to deliver drugs such as siRNA to increase M1 TAMs or inhibit M2 TAMs at tumor sites." (PMID 35859703, 2022). "In addition, the treatment of SIRPα-exosomes can promote T cell infiltration in syngeneic tumor mouse model and increase the possibility of CD47 targeting therapy to release innate and adaptive antitumor responses." (PMID 34973131, 2022). "Furthermore, SHP1 is a key inhibitor of SIRPα (on macrophage)-CD47 (on tumor) for “don’t eat me” signaling." (PMID 36686648, 2022). "CD47 is an innate immune checkpoint that interacts with receptor signaling regulatory protein α (SIRPα), thereby inhibiting phagocytosis by macrophages, and inhibition of the CD47/SIRPα signaling pathway may also limit tumor growth." (PMID 36080373, 2022). "Moreover, when mice previously treated with the SIRPα inhibitor SL-172154 were rechallenged with a second colorectal tumor on the opposite flank, 60% of the mice rejected the tumor, suggesting development of T cell immune memory." (PMID 36439116, 2022). "Similarly, to escape immune system tumor cells express on their surface CD47 that functions as an inhibitor of phagocytosis following its interaction with the signal-regulatory protein alpha (SIRPα) expressed on macrophages cell surface." (PMID 35493456, 2022). "Although the CD47- SIRPα axis blockade revealed beneficial effects in the struggle against brain tumors, additional pro-phagocytic stimuli are required for complete eradication of the tumor." (PMID 35054787, 2022). "In the fourth pathway, the inhibition of CD47 or SIRPα can induce tumor cell apoptosis, which could be attributed to the direct ligation of CD47 rather than the caspase-dependent pathway." (PMID 35860564, 2022). "SIRPα and CD68 were expressed by tumor-associated macrophages (Μφ, TAMs)." (PMID 35406573, 2022). "CD47 is a cell surface protein on tumor cells that binds to SIRPα (signal regulatory protein alpha) on macrophages, and the protein-protein interaction activates the cytoplasmic domain of SIRPα to trigger intracellular signals leading to inhibition of phagocytic activity." (PMID 36509828, 2022). "Indeed, the blockade of the SIRPα/CD47 pathway reportedly potentiates T cell recruitment into tumor nest and antitumor immune activity in some tumor types." (PMID 35241649, 2022). "SIRPα expression is upregulated in tumor cells and usually indicates worse prognosis." (PMID 36253800, 2022). "Notably, despite the excellent clinical performance shown by CD47/SIRPα antibodies, the limitations of antibody drugs, including poor tumor permeability, undesirable oral bioavailability and poor stability, hinder their clinical application." (PMID 36080360, 2022). "Blocking the CD47/SIRPα cross talk has been shown to enhance anti-tumor activities." (PMID 35978372, 2022). "Therefore, blocking the CD47/SIRPα cross talk activates the innate and adaptive immune systems, leading to tumor cell destruction." (PMID 35978372, 2022). "SIRPα and CD68 were expressed, to a varying extent, by tumor-associated macrophages (Μφ, TAMs)." (PMID 35406573, 2022). "CD47 as another immune checkpoint is also overexpressed on the most tumor cells, and it often interacts with signal regulatory protein α (SIRPα) on phagocytic cells, which activates “don’t eat me signal” of CD47 and leads tumor cells to escape from immune monitoring." (PMID 36733388, 2022).
tumor (continued). "Exosomes that carry SIRPα variants may antagonize the interaction between CD47 and SIRP, enhancing tumor phagocytosis and enhancing an effective antitumor T cell response." (PMID 35214129, 2022). "Although correlation among the expression of CD68, SIRPα, and PD1 was revealed, further studies evaluating the other SIRPα-expressing or PD1-expressing cells will improve the understanding of the association between its expression and the tumor microenvironment in ICCs." (PMID 35317832, 2022). "In conclusion, CD47 mAbs or SIRPα fusion combined with other anti-tumor drugs could be an effective treatment option for AML or MDS patients." (PMID 35978372, 2022). "It is, therefore, likely that immunotherapy targeting the CD47/SIRPα axis may enhance anti-tumor response by activating both macrophage-mediated innate and T-cell adaptive immunity." (PMID 35406573, 2022). "However, experimental administration of monoclonal antibodies or soluble SIRPα (Fc-fusion) that bind CD47 and block the CD47-SIRPα signaling pathway promotes tumor cell phagocytosis, inhibits tumor growth in mice, and increases survival." (PMID 36369063, 2022). "CD47-mediated immune evasion relies on its different cellular functions; however, many studies have mostly focused on its interaction with the signal-regulatory protein alpha (SIRPα), whose downstream effect of phosphorylation is the inhibition of tumor cell phagocytosis." (PMID 35054787, 2022). "Treatment with a combination of OH2 and anti-SIRPα effectively inhibited tumour growth and significantly prolonged the survival time of the mice, and this result was more obvious in the mouse model with a larger tumour volume at the beginning of the treatment." (PMID 36310169, 2022). "Furthermore, the function of the CD47/SIRPα axis was established in the late 2000s and has been termed the first tumor phagocytosis-related checkpoint (also known as the macrophage “don’t eat me” signal)." (PMID 35317832, 2022). "In vivo distribution experiments showed that CBD–SIRPα-Fc accumulated in tumor tissue more effectively compared to unmodified SIRPα-Fc, probably due to the exposed collagen in the tumor vascular endothelium and stroma resulting from the abnormal vessel structure." (PMID 36080360, 2022). "Upregulated expression of CD47 on tumor cells increases the interaction with SIRPα on the myeloid cell membrane, leading to a release of the “don’t eat me” signal to evade the phagocytosis of myeloid cells, which is one of the primary mechanisms of cancer and disease formulation." (PMID 35557862, 2022). "In addition to the inhibition of macrophage-mediated phagocytosis, CD47 expressed on tumor cells was shown to inhibit the detection of tumor cell–derived mitochondrial DNA by SIRPα on DCs, resulting in attenuation of type I IFN production by DCs." (PMID 35454882, 2022). "The cluster of differentiation 47 (CD47) is universally expressed on normal cells, and tumor cells regulate phagocytosis and cytotoxic activity of myeloid cells through interaction with the signal‐regulatory protein α (SIRPα) receptor on myeloid lineage derived cells." (PMID 36054073, 2022). "Therefore, decorating exosomes surface with dibenzocyclooctyne-derivatized SIRPα antibodies can suppress tumor cells." (PMID 36678695, 2022). "Myeloid progenitor cells from high-risk MDS patients additionally overexpress CD47, which is a surface anti-phagocytic molecule abnormally expressed on tumor cells that binds to its receptor Signal regulatory protein alpha (SIRPa) on macrophages and inhibits phagocytosis, counteracting CRT." (PMID 36428749, 2022). "Since CD47 is expressed by all cells throughout the body, and SIRPα is only expressed on the neuronal cells and myeloid cells, developing novel strategies to against SIRPα holds much more superiority to enhance tumor‐phagocytosis of macrophages and reduce side effects." (PMID 37323705, 2022).
tumor (continued). "Although the significance of CD47 expression in tumors has been identified in many tumor types, the role of SIRPα in ICC patients remains unclear." (PMID 35317832, 2022). "The engineered vector SIRPα-Fc-VV replicated successfully in tumour cells, induced the killing of tumour cells in vitro by M1 and M2 macrophages after the addition of conditioned infected cell media to co-cultures, and recruited macrophages and monocytes to tumours in vivo." (PMID 36140243, 2022). "However, a variety of tumor cells have upregulated CD47 protein on their surface, which can interact with signal regulatory protein alpha (SIRPα) on M1-like TAMs and trigger evasion of tumor cells from macrophage recognition." (PMID 34138357, 2021). "In addition, the expression of SIRPA and macrophage markers (CD68 and CD163) in tumor-associated immune cells (TAIs) was analyzed." (PMID 33799989, 2021). "In addition to promoting the phagocytosis of live tumor cells by blocking CD47/SIRPα interaction, inhibiting the phagocytosis of apoptotic tumor cells by TAMs is another promising tumor immunotherapy strategy." (PMID 33919979, 2021). "Also, the SIRPα-enriched exosomes can promote the T cell infiltration in the mouse model, and inhibit the tumor growth ultimately." (PMID 34852849, 2021). "A combination of SIRPα and PD-1 blockade could result in durable anti-tumor immunity by facilitating monocyte activation, dendritic cell activation, and T cell effector functions." (PMID 34068552, 2021). "Indeed, SIRPα mediates inhibition that not only restrains macrophages from phagocytosis of tumor cells but also dampens their capacity to exert proinflammatory responses and immunogenic antigen presentation that drive antitumor adaptive immunity." (PMID 34050181, 2021). "The engagement of tumor cell CD47 with SIRPα expressed on the surface of monocytes/macrophages may produce inhibitory signals which inhibit phagocytosis." (PMID 33629544, 2021). "Although TAMs maintain the ability to phagocytose tumor cells to some extent, tumor cells often express high levels of CD47 molecules that bind to signal regulatory protein α (SIRPα) on the surface of TAMs, sending the “don’t eat me” signal and inhibiting the phagocytic activity of TAMs." (PMID 35070992, 2021). "Consisting of human IgG4-Fc region of anti-PD-1 mAb and extracellular domain (ECD) of SIRPα, it achieves the synergistic anti-tumor effects by simultaneously activating both innate and acquired immune responses to suppress tumor immune escape and release immune suppression at immune checkpoints." (PMID 34305918, 2021). "Therefore, further investigation is required to unravel the multifaceted capacity of SIRPα that regulates macrophages and thereby drives the entire tumor-immune response to resist RT." (PMID 34050181, 2021). "In addition to activating adaptive immune components against cancer, activated intratumoral Sirpα−/− macrophages by irradiated tumor cell-released DAMPs also elicit a robust proinflammatory response that reshapes the TME to favor tumor elimination." (PMID 34050181, 2021). "Disruption of SIRPα:CD47 signaling also increased NK cell activation and cytotoxicity while CD47 overexpression inhibited cytotoxic killing of tumor or MHC-deficient target cells in vitro; importantly, this latter observation was dependent upon SIRPα expression on NK cells." (PMID 34603322, 2021). "Another mediator of tumor immune evasion in addition to TAMs is the CD47/SIRPα axis." (PMID 34573091, 2021). "A blockade of CD47/SIRPα could reactivate the phagocytosis of macrophages and enhance the anti-tumor immunity." (PMID 34068552, 2021). "At this stage, it remains unknown how SIRPα mediates such a strong immunosuppressive response in the TME to bolster tumor resistance to RT." (PMID 34050181, 2021). "In addition, CD47/SIRPα interaction also has roles in tumor cell apoptosis, proliferation and migration." (PMID 34944850, 2021).
tumor (continued). "We also analyzed BMDMs from Sirpα−/− and WT mice prior to tumor engraftment." (PMID 34050181, 2021). "Moreover, the anti-SIRPα Ab treatment shows a synergistic effect in combination with rituximab and anti-programmed cell death 1 (PD-1) on tumor formation in mice." (PMID 33763066, 2021). "Tumor numbers were significantly reduced by SIRPα antibody treatment." (PMID 34667145, 2021). "Anti-SIRPα antibodies can enhance phagocytosis when combined with tumor-opsonizing anti-CD47 mAbs." (PMID 34717705, 2021). "JMT601 (CPO107) blocked the expression of CD47 on tumor cells and SIRPα on macrophages." (PMID 34717705, 2021). "Moreover, relieving the SIRPα break on macrophages promotes intra-tumoral chemokine secretion, T-cell migration in tumor bed and improves T-cell immunotherapy responses." (PMID 34276698, 2021). "In the present study, our specific focus has been to investigate whether the CD47/SIRPα axis is involved in the VES-induced anti-tumour effect." (PMID 34093795, 2021). "Likewise, anti-SIRPα antibodies have shown preclinical activity as a single agent or in combination with a tumor-targeted agent." (PMID 33925464, 2021). "SIRPα (signal regulatory protein α)–CD47: The SIRPα receptor is expressed by tumor-associated macrophages, and binding with the CD47 ligand expressed by tumor cells induces the phosphorylation of SIRPα with a final inhibitory effect on the phagocytosis process." (PMID 34207243, 2021). "In MC38 or Pan02 tumor-eradicated Sirpα−/− mice, we performed tumor re-engraftment to determine whether long-term antitumor immunity had manifested." (PMID 34050181, 2021). "Furthermore, i.t. injection of Sirpα−/− macrophages led to an increase in the expression of immunogenic antigen presentation machinery (MHC-I/II, CD80/86, and OX40L) on endogenous WT tumor-associated macrophages." (PMID 34050181, 2021). "Moreover, exosomal signal regulatory protein α (SIRPα) proteins can effectively lead to phagocytic elimination of tumor cells." (PMID 35047512, 2021). "Moreover, disruption of the CD47/SIRPα axis reduces the ability of tumor cells to escape phagocytosis." (PMID 34573091, 2021). "However, the sera from tumor-eradicated Sirpα−/− mice only delayed the growth of small tumors (<100 mm3) and failed to control the growth of large tumors (>200 mm3) in WT recipient mice." (PMID 34050181, 2021). "Corresponding IHC/IF of tumor area or ex vivo flow cytometry analysis of SIRPα expression could also be used to assess how well the radioactive signals from the tracer and the expression of the marker match." (PMID 34917090, 2021). "The effect of inhibiting CD47 in signaling pathways, other than SIRPα, is less studied and might be different according to tumor type." (PMID 34195295, 2021). "In many sarcomas, including chordomas, dedifferentiated liposarcomas, and osteosarcomas, CD47 was observed to be highly expressed on tumor cells along with SIRPα expression on macrophages, suggesting a means of immune evasion in these tumors through this inhibitory axis." (PMID 34440251, 2021). "Next to counteracting the don’t-eat-me signal, nanobodies targeting SIRPα could also be used to deplete tumor-promoting myeloid cells, which facilitate GBM development and protect it from therapeutic treatments." (PMID 34917090, 2021). "Potential limitations of targeting the CD47/SIRPα axis includes the ability to target agents into the tumor and toxicity such as cytopenias, which may potentially be overcome by novel therapeutic strategies." (PMID 34944850, 2021). "The CD47/SIRPα axis was defined as an innate immune checkpoint in several tumor models, which stimulates antigen-presenting cell function and consequently the adaptive T cell-mediated anti-tumor immunity." (PMID 32899714, 2020). "The CD47/SIRPα interaction blocks macrophages from participating in tumor killing." (PMID 33178841, 2020).